CDKN1C (cyclin dependent kinase inhibitor 1C)
Diseases named in the same sentence as CDKN1C in open-access papers (continued):
Sharing a sentence is not in itself a finding about the gene and the disease.
Hydrocephalus (2 papers, 2020). Hydrocephalus is an active distension of the ventricular system of the brain resulting from inadequate passage of CSF from its point of production within the cerebral ventricles to its point of absorption into the systemic circulation. "The previous study of maternal Cdkn1c cKO mice concluded that the thinning of the neocortex also apparent in these mice was a result of the hydrocephalus caused by impaired development of the SCO30." (PMID 32024956, 2020). "Our results revealing a thin neocortex without apparent hydrocephalus in the paternal Cdkn1c cKO brain thus indicates that this neocortical phenotype is not due to hydrocephalus, at least not in these animals." (PMID 32024956, 2020). "However, the neocortical thinning detected in our paternal Cdkn1c cKO mice appears to be independent of any effect on the SCO, given the absence of hydrocephalus." (PMID 32024956, 2020).
Hyperinsulinemia (2 papers, 2021 to 2025). An increased concentration of insulin in the blood. "In BWS, imprinting defects lead to loss of expression of cell-cycle inhibitor CDKN1C (p57Kip2), resulting in unchecked beta cell expansion and excessive beta cell mass, which causes hyperinsulinemia, and hypoglycemia." (PMID 34025578, 2021).
influenza (2 papers, 2015 to 2020). An acute viral infection of the respiratory tract, occurring in isolated cases, in epidemics, or in pandemics; it is caused by serologically different strains of viruses (influenzaviruses) designated A, B, and C, has a 3-day incubation period, and usually lasts for 3 to 10 days. "We observed a downregulation of CDKN1C transcript in the severe influenza cases compared to moderate influenza cases (p < 0.0001)." (PMID 32066441, 2020). "In addition to IFI27 and PI3 that have the largest expression difference between influenza and HRV, CDKN1A and CDKN1C, which are essential genes involved in cell cycle control, appeared to be differentially expressed specifically in influenza virus infection." (PMID 26070066, 2015).
lung adenocarcinoma (2 papers, 2020 to 2021). A carcinoma that arises from the lung and is characterized by the presence of malignant glandular epithelial cells. "On the transcriptomic level, TCGA database analysis found that CDKN1C was significantly overexpressed in the normal tissue, compared with multiple tumours, such as BC, bladder urothelial carcinoma, kidney carcinoma and lung adenocarcinoma." (PMID 34464504, 2021).
Lung mucoepidermoid carcinoma (2 papers, 2019 to 2024). "In mucoepidermoid carcinoma of the lung, HMOX1 overexpression was also associated with the inhibition of cell-cycle progression proteins Cyclin D1 (CCND1) and CCND2, and the stimulated transcription of the cell-cycle arrest proteins Gastrin (GAS) and Cyclin-dependent kinase inhibitor 1C (CDKN1C)." (PMID 31717324, 2019).
rhabdoid tumor (2 papers, 2009 to 2013). An aggressive malignant embryonal neoplasm usually occurring during childhood. "The relevance of impaired CDKN1C expression in RT cell lines to the aetiology of RT was further ascertained by examination of clinical rhabdoid tumor specimens." (PMID 19221586, 2009). "Our observations suggest that maintenance of CDKN1C expression plays a critical role in preventing rhabdoid tumor growth." (PMID 19221586, 2009). "As HDAC inhibition has been shown to restore imprinted tumor suppressors such as CDKN1C in rhabdoid tumors, we hypothesized that HDACi might generally compensate the missing chromatin remodeling function caused by SMARCB1 loss." (PMID 23764045, 2013). "CDKN1C expression was also shown to be generally absent in clinical specimens of rhabdoid tumor, however CDKN1A and CDKN1B expression persisted." (PMID 19221586, 2009).
type 2 diabetes (2 papers, 2009 to 2012). "KCNQ1 is located on chromosome 11p15.5, a region that also contains other genes which have previously been associated with type 2 diabetes, e.g., CDKN1C." (PMID 19516902, 2009). "In this context it is important to notice that polymorphisms in the neighbouring CDKN1C have been associated with increased birth weight, and that variation in the CDKN family (CDKN2A/B locus; chromosome 9p21) has been associated with type 2 diabetes in recent GWAS- and GWAS-replication studies." (PMID 19516902, 2009).
anorexia nervosa (1 paper, 2023). A disorder most often seen in adolescent females characterized by a refusal to maintain a minimally normal body weight, an intense fear of gaining weight, a disturbance in body image, and, in postmenarcheal females, the development of amenorrhea. "In addition, CDKN1C and DLK1 appear to be hormonally regulated, with the former decreasing after expose to estradiol in endometrial cancer cells, while the latter decreasing after treatment with estradiol in girls with anorexia nervosa or human uterine leiomyoma cells." (PMID 37700362, 2023).
asthma (1 paper, 2025). "Interestingly, there was relative absence of respiratory system involvement in all molecular causes except CDKN1C, where asthma was reported in 18%." (PMID 41430624, 2025).
chronic inflammatory demyelinating polyneuropathy (1 paper, 2017). "Of note, Joshi and coworkers recently demonstrated that SCs show an altered expression of c-Jun and Cdkn1c and that their pro-regenerative functions are diminished in a model of chronic inflammatory demyelinating polyneuropathy (CIDP)." (PMID 28261057, 2017).
COVID-19 (1 paper, 2022). A disease caused by infection with severe acute respiratory syndrome coronavirus 2. "Many of the cell cycle-related genes, such as aurora kinase B (AURKB) and cyclin-dependent kinase inhibitor 1A (CDKN1A, p21), were consistently upregulated in a COVID-19 specific manner, while some were consistently downregulated, such as cyclin-dependent kinase inhibitor 1C (CDKN1C, p57)." (PMID 35991542, 2022).
cutaneous T-cell lymphoma (1 paper, 2020). "CDKN1C, known as a tumor suppressor gene, is found to be decreased in patients with cutaneous T-cell lymphoma, which is the most common lymphoma of the skin." (PMID 32015692, 2020).
Dengue (1 paper, 2022). "Because CD38 and CDKN1C express differently in three stages, we speculate that they can be used as biomarkers with staging characteristic to distinguish clinical stages for Dengue patients." (PMID 35918744, 2022).
depression (1 paper, 2016). "In an initial pilot study, expression of the imprinted genes PEG3, PEG10, PHLDA2 and CDKN1C was analysed in a cohort of placentas (n = 75), which included a subset of women (n = 7) who had diagnosed depression during pregnancy." (PMID 27523184, 2016).
gastric tumors (1 paper, 2009). "In gastric tumors both mechanisms silence CDKN1C and expression can be restored by demethylating reagents in cases where the promoter is hypermethylated or by HDACi in cases where promoter histones are deacetylated." (PMID 19221586, 2009).
hemihyperplasia (1 paper, 2021). "Previous studies of BWSp/SRSp reported the extreme rarity of hemihyperplasia/hemihypoplasia in patients with CDKN1C mutations." (PMID 34627330, 2021). "This may be because the underlying molecular defect of CDKN1C mutations is a germline mutation that affects all cells in the body rather than a somatic mosaicism and because our study population comprised isolated hemihyperplasia/hemihypoplasia patients." (PMID 34627330, 2021). "CDKN1C sequencing is therefore thought to be unnecessary in patients with isolated hemihyperplasia/hemihypoplasia." (PMID 34627330, 2021).
invasive breast carcinoma (1 paper, 2008). A carcinoma that infiltrates the breast parenchyma. "Cancer and paired normal epithelium from ten invasive breast cancers were analyzed for CDKN1C RNA expression by qPCR." (PMID 18325103, 2008).
large intestinal tumors (1 paper, 2017). "Accordingly, we observed an increase of Cdkn1b and Cdkn1c gene expression only in the ubiqDll4-/- small and large intestinal tumors relatively to the controls and to the endoDll4-/- mice." (PMID 28086833, 2017).
metastatic tumors (1 paper, 2005). "CDKN1C, a tumor suppressor gene that regulates cell proliferation, was recently found to be downregulated in metastatic tumors." (PMID 16280042, 2005).
myeloid leukemia (1 paper, 2021). A clonal proliferation of myeloid cells and their precursors in the bone marrow, peripheral blood, and spleen. "MBD2 expression was negatively correlated with CDKN1C expression in clinical myeloid leukemia samples." (PMID 34789717, 2021).
myocardial infarction (1 paper, 2020). Gross necrosis of the myocardium, as a result of interruption of the blood supply to the area, as in coronary thrombosis. "One of the genes included in the KCNQ1OT1 imprinted cluster, cyclin-dependent kinase inhibitor 1C (CDKN1C), was postulated as a novel female-specific biomarker of left ventricular dysfunction after myocardial infarction." (PMID 32664454, 2020).
myopia (1 paper, 2023). "Taken together, we suppose that in high myopia, NOTCH2 signalling inhibition could accelerate secondary lens fibre cell differentiation by activating CDKN1C, the differentiation initiator, and promote accumulation of β/γ crystallin, the specific structural proteins of LFCs, by activating MAF." (PMID 36717696, 2023).
orchitis (1 paper, 2021). Inflammation of one or both testes due to viral or bacterial infections.
Ovarian cyst (1 paper, 2019). The presence of one or more cysts of the ovary. "Additionally, a somatic p.(Glu56Gly) likely pathogenic was identified in CDKN1C that was similarly only present in the ovarian cyst." (PMID 30761771, 2019). "Remarkably, the ovarian cyst also had a second likely pathogenic variant in PIK3CA, c.2135 T>C (p.(Leu712Pro), VAF <10%), and a third likely pathogenic variant in CDKN1C, c.167A>G (p.(Glu56Gly), VAF 36%–45%)." (PMID 30761771, 2019).
pancreatic ductal adenocarcinoma (1 paper, 2018). An infiltrating adenocarcinoma that arises from the epithelial cells of the pancreas. "Since the cell cycle regulator protein p57KIP2 (encoded by the CDKN1C gene, hereafter p57) had been reported to mediate synergistic induction of apoptosis by combined HDAC and BET inhibition in pancreatic ductal adenocarcinoma, we evaluated its expression in four UCCs after treatment." (PMID 29312470, 2018).
Parkinson disease (1 paper, 2008). A progressive degenerative disorder of the central nervous system characterized by loss of dopamine producing neurons in the substantia nigra and the presence of Lewy bodies in the substantia nigra and locus coeruleus. "We also examined expression of H19, IGF2, and CDKN1C in laser-captured dopamine neurons, identified on the basis of neuromelanin presence, from a series of human postmortem RNA samples from human cases of Parkinson's disease and controls." (PMID 18183302, 2008).
prostate (1 paper, 2013). "In our opinion, especially the CDKN1C gene, negative regulator of cell proliferation alterated in many tumors may be important in prostate carcinogenesis." (PMID 23288724, 2013).
thymic lymphomas (1 paper, 2018).
thyroid (1 paper, 2025). "Conversely, CDKN1C expression was reduced in carcinoma samples, particularly FTC, indicating its potential utility in distinguishing FTC from other thyroid pathologies, consistent with its role as a tumor suppressor." (PMID 40722651, 2025).
trichorhinophalangeal syndrome type I (1 paper, 2024). An autosomal dominant malformation syndrome caused by mutations in TRPS1 characterized by distinctive craniofacial and skeletal abnormalities. "Previous studies show that miR-222-3p has an oncogenic effect by regulating MMP2 (matrix metalloproteinaza), MMP9, TRPS1 (trichorhinophalangeal syndrome type 1), and CDKN1C/p57 (cyclin-dependent kinase inhibitor 1C)." (PMID 38542261, 2024).
urothelial carcinoma (1 paper, 2024). A malignant neoplasm derived from the transitional epithelium of the urinary tract (urinary bladder, ureter, urethra, or renal pelvis). "Interestingly, CDKN1C under-expression is also associated with pluripotency and tumorigenesis in a variety of cancers such as breast, gastric, pancreatic, and urothelial carcinomas." (PMID 39684302, 2024).
tumor (114 papers, 2004 to 2025). "A number of imprinted tumor suppressor genes such as RB1, TP73, and CDKN1C showed copy number loss or the loss of expression in many tumor cell lines." (PMID 40414875, 2025). "CDKN1C is a key regulator of cell growth and proliferation, and aberrant expression is observed in syndromes with overgrowth, tumor predisposition, and congenital malformations, such as Beckwith–Wiedemann syndrome, notably in mouse embryos and fetuses." (PMID 37435029, 2023). "Our study adds evidence that tumour development in patients with BWSp and CDKN1C variants is infrequent, but it is extremely relevant to the patient’s follow-up and supports the high heterogeneity of BWSp clinical features associated with CDKN1C variants." (PMID 35954470, 2022). "This study adds evidence of the incidence of tumours in patients with BWSp caused by pathogenic CDKN1C variants, which has an important consequence in clinical management, follow-up, and genetic counselling." (PMID 35954470, 2022). "As a tumour suppressor gene, CDKN1C is implicated in various human cancers and Beckwith‐Wiedemann Syndrome." (PMID 34464504, 2021). "The four main molecular subtypes of BWS (KCNQ1OT1:TSS-DMR-LOM, H19/IGF2:IG-DMR -GOM, UPD, and CDKN1C mutations) are characterized by specific genotype-phenotype correlation to tumor development risk." (PMID 33101381, 2020). "CDKN1C (encoding p57KIP2) is known to be silenced by methylation in many tumour types so perhaps these HT6244-R, H6244-R and L6244-R cells exemplify this." (PMID 35582726, 2019). "These include critical cell cycle regulating tumor suppressors such as cyclin dependent kinase inhibitors CDKN1C (p57) and the cell cycle and differentiation associated BTG2." (PMID 20927380, 2010). "We tested for associations between AI/LOH at each DNA marker,CDKN1C mRNA expression and protein staining, and subject age, tumor histology, grade, ER/PR or HER2 status." (PMID 18325103, 2008). "Although there is a relatively high prevalence of this tumour type in patients with CDKN1C variants, we cannot be certain that this neoplasm is directly linked to the loss-of-function CDKN1C variant or how this kind of variant can somehow affect tumour predisposition." (PMID 35954470, 2022). "Moreover, the mutation/inactivation of CDKN1C in the cancer-susceptible Beckwith–Wiedemann syndrome also implied its importance in tumor suppression." (PMID 34283053, 2021). "Besides, the association between CDKN1C expression and enriched gene sets and pathways, as well as tumour immune microenvironment (TIM), were investigated in BC patients." (PMID 34464504, 2021). "In addition to T-ALL, downregulation of CDKN1C has been observed more frequently in a wide variety of human tumours associated with a strengthening of cell proliferation." (PMID 29661169, 2018). "The overexpression of CDKN1C may cause cell cycle arrest in human tumour cell lines, and this inhibitory effect may be reversed by siRNAs against the CDKN1C gene." (PMID 29661169, 2018). "In this study, we report on 10 additional patients with BWSp and CDKN1C variants and review the clinical spectrum of all of these previous cases (for a total of 21 cases of BWSp), with the aim of improving the genotype–phenotype correlations and calculating the tumour risk." (PMID 35954470, 2022). "Whether the aetiology of these cancers is primarily attributable to the loss of CDKN1C expression in target tissues is currently uncertain, and it would be wise to maintain the tumour screening protocols in IC2 deletion cases, currently performed for loss of methylation cases." (PMID 22205991, 2011). "Some studies have shown that reduced expression of CDKN1C plays a role in tumor progression, supporting its role as a tumor suppressor." (PMID 40722651, 2025). "In our tumor samples, we observed the overexpression of S-phase kinase-associated protein 2 (SKP2) and downregulation of cyclin-dependent kinase inhibitor 1C (CDKN1C)." (PMID 40266039, 2025).